INS (insulin)
Diseases named in the same sentence as INS in open-access papers (continued):
Sharing a sentence is not in itself a finding about the gene and the disease.
diabetes (continued). "This 12-week cohort study recruited patients from 18 general practices in the United Kingdom with non-insulin treated diabetes who were initiating or changing dose of oral glucose-lowering medication." (PMID 24667212, 2014). "If β cells were shown to increase insulin levels, then Imatinib can be a candidate therapy for diabetes including type 1 and type 2 diabetes." (PMID 24835010, 2014). "Eight patients continued on sitagliptin for the duration of the study (44.9 ± 10.9 months) but required addition of other diabetes medications to maintain glycemic control (oral agents, n = 4; insulin, n = 4)." (PMID 24817885, 2014). "One of the disadvantages of the study was the inability to distinguish between diabetes types, although only eight individuals started with insulin treatment under the age of 35 years, suggesting a minor contribution of patients with type 1 diabetes." (PMID 25419576, 2014). "The weight loss was associated with a correction in abnormalities due to osmotic diuresis and glucose intolerance, resulting from inadequate insulin secretion or hyperlipidemia in diabetes mellitus." (PMID 23579248, 2014). "The results of multiple regression analysis with ΔBW as the dependent variable indicated that ΔBW at 24 weeks of lira administration was higher with higher baseline daily insulin doses and longer duration of diabetes." (PMID 24578756, 2014). "Myosin light chain kinase (MLCK), the enzyme that activates NMMII, has been shown to be diminished in diabetes and this dysregulation reversed by insulin." (PMID 25705628, 2014). "Duration of diabetes, pubertal stage, mean HbA1c values during the year preceding the study, total daily insulin dose (U/kg/day), BMI, BMI SDS, as well as TG, TC, HDL and LDL values in the control and carb counting groups were similar at baseline." (PMID 24932599, 2014). "They found that, Vitamin D improved the deleterious biochemical impact of diabetes mellitus, likely by increasing insulin secretion and sensitivity, improving the β-cell function, and decreasing the number of pro-inflammatory cytokines and insulin resistance." (PMID 25340161, 2014). "Although GA is a superior index to HbA1c for subjects with anemia or CKD, duration of diabetes as well as insulin secretory function should be taken into consideration when interpreting GA values." (PMID 25265016, 2014). "Ketoacidosis is more severe in states of glycogen depletion, as seen in individuals with history of excess alcohol intake, and is augmented by lower insulin levels and perhaps higher levels of counterregulatory hormones as a result of volume depletion." (PMID 24963418, 2014). "Deficiency of specific vitamins and minerals play important roles in glucose metabolism and insulin signalling contribute to the development of diabetes." (PMID 25184241, 2014). "Several other therapeutic approaches have also been used as potential treatment for diabetes, including sulfonylureas, thiazolidinediones, metformin, and insulin." (PMID 24738000, 2014). "The GA group had higher prevalence of ASA class III and IV patients (91.14% vs 90.04%), COPD (10.51% vs 9.51%), diabetes on insulin (9.69% vs 8.64%), and central nervous system disease (43.33% vs 41.18%) than RA group." (PMID 26023678, 2014). "In most of the herbal remedies used in treating diabetes, the mechanisms of action have centered on insulin signaling pathways, GLUT-4 receptor translocation and the PPAR gamma activation." (PMID 25331834, 2014). "Chronic inflammation-mediated β-cell apoptosis is known to decrease β-cell mass in diabetes leading to reduced insulin secretion." (PMID 24974801, 2014). "The level of transcription for the receptor ADRβ3 was decreased by diabetes in eWAT and rWAT but unaltered in scWAT and a reduction of transcription level was observed in response to insulin treatment in the same depots." (PMID 25170835, 2014).
diabetes (continued). "Insulin resistance in the liver and other human tissues can lead to compensatory increases in insulin production and secretion by pancreatic β cells, a facultative response that fails during pathogenesis of type 2 diabetes mellitus (T2DM)." (PMID 25101872, 2014). "Fasting levels of blood glucose (FBG), glycosylated hemoglobin (HbA1c), and serum insulin were measured in 100 diabetics and 100 age-matched controls before and during Plasmodium falciparum malaria." (PMID 25587486, 2014). "This is partly consistent with work suggesting that diabetes remission is more common in younger, leaner, more insulin sensitive patients with adequate beta-cell function at baseline." (PMID 24736741, 2014). "Patients with diabetes are characterized by an impaired ability to secrete insulin and/or a decreased sensitivity to insulin." (PMID 24592256, 2014). "The majority of these patients were Caucasians, had gone to more medical clinical visits in the previous year and were under carbohydrate counting and diets recommended by diabetes societies’ guidelines and using more complex schedules of insulin therapy." (PMID 24607084, 2014). "Difficulties accessing endocrinologists and diabetes nurse educators because of cost and limited availability can lead to delays in starting insulin, and avoidable periods of hyperglycaemia." (PMID 24528528, 2014). "CSbnp contribution in diabetes control was profound and a remarkable response was recorded in the test animals with recovery to nearly normal insulin levels and reduced glycated hemoglobin parameters." (PMID 24991800, 2014). "The combination of inadequate insulin secretion and insulin resistance is the primary cause of IGT and subsequent diabetes in adults." (PMID 24755002, 2014). "In 2004 396,481 persons in Belgium were reimbursed at least one package of diabetes medication of whom 104,780 were prescribed insulin therapy; in 2010 this was respectively 489,559 and 136,753." (PMID 25145469, 2014). "Diabetes, a disorder of metabolism with defects in either insulin secretion, insulin action or both, is increasing globally due to population growth, aging, urbanization, unhealthy eating habits, and increasing prevalence of obesity and physical inactivity." (PMID 24416185, 2014). "Whereas, insulin dose was continued unchanged in 64% of the patients with diabetes (both type 1 and type 2 diabetes)." (PMID 24559109, 2014). "The first group consisted of eight subjects with past history of ketoacidosis and were treated with insulin." (PMID 25945127, 2014). "Selected ion flow tube mass spectrometry (SIFT-MS) was used to monitor the breath of eight patients with type 1 diabetes mellitus during “insulin clamp” studies in which insulin and glucose were infused into patients to lower blood glucose levels." (PMID 26852676, 2014). "Some studies have stated that the elimination of chronic hyperglycemia with exogenous insulin, if started shortly after diabetes, suppresses the diabetogenic actions of STZ." (PMID 24842144, 2014). "Section A elicited information on their demographics characteristics and participation in update courses, and exercise, while section B assessed knowledge of insulin use using the Michigan Diabetes Research and Training Centre's Brief Diabetes Knowledge Test." (PMID 24397956, 2014). "BIX, at doses that show no toxic effects, was as effective as metformin to decrease blood glucose levels and more effective than metformin and insulin to improve the dyslipidemia in STZ-induced diabetes." (PMID 24624139, 2014). "In patients with type 2 diabetes mellitus on insulin treatment, ATGL protein was borderline increased in subcutaneous adipose tissue, and G0S2 mRNA and protein were decreased when insulin treatment was withheld and patients were hyperglycaemic." (PMID 25118138, 2014). "Adiponectin also helps cells respond to insulin, a hormone that regulates blood sugar levels, and thus helps to prevent diabetes." (PMID 25339419, 2014).
diabetes (continued). "There were also a higher proportion of members of low SES, ethnic minorities, insulin users, and those with a long duration of diabetes in the poorly controlled group." (PMID 25259843, 2014). "Combined GLP-1 receptor agonist and insulin therapy has shown promising results in patients who are modestly obese and have a longer duration of diabetes." (PMID 25349635, 2014). "Clinically, steroid diabetes or worsened glycemic control in diabetic subjects is usually treated with insulin injections, oftentimes mixtures containing a high proportion of a direct acting insulin analogue to curb prandial glycemia." (PMID 24423471, 2014). "We aimed to determine if ultrastructural morphometric parameters of the renal nerves are affected by short term and/or long term experimental diabetes and if insulin treatment reverses these alterations." (PMID 24387617, 2014). "The insulin signaling pathway plays important roles in the pathogenesis of type 2 diabetes mellitus." (PMID 24447392, 2014). "At the present, the current methods for cure of diabetes include exercise, diet, and the use of oral hypoglycemic agents as well as insulin therapy." (PMID 24495344, 2014). "It is important to note that all these changes related to oxidative stress in diabetes were prevented by insulin treatment." (PMID 25469699, 2014). "The current pharmacological treatment of diabetes is aimed at maintaining strict control of glycemia using oral hypoglycemic agent and insulin or combination of both." (PMID 24688431, 2014). "Factors associated with such dysregulation of hepatic apoB100 metabolism include insulin resistant states such as obesity, metabolic syndrome, and type 2 diabetes mellitus." (PMID 25246308, 2014). "Diabetes also affects glucose metabolism, insulin signaling, and mitochondrial function in the brain." (PMID 25250014, 2014). "In diabetes, insulin secretion is insufficient or there is insulin resistance, which can reduce the glucose utilisation and glycogen synthesis, inducing abnormal increases in gluconeogenesis." (PMID 25177729, 2014). "This amyloid fibril in human pancreas is able to replace the β cell performing the insulin secretion in pancreas, which results in amyloid fibril-driven inhibition of insulin secretion leading to diabetes." (PMID 24551113, 2014). "One report, using an animal model, found that galectin-3+/+mice developed delayed and sustained hyperglycemia in streptozotocin-induced diabetes, mononuclear cellular infiltration and reduced insulin content of islets." (PMID 25302080, 2014). "The multivariate analysis revealed a second-order interaction between diabetes duration, the presence of DR, and insulin therapy (p = 0.005)." (PMID 25138117, 2014). "Sixty-eight (88.3%) patients with type 2 diabetes were treated with oral anti-diabetes, 2 (2.5%) with a combination of insulin and oral anti-diabetics and 7 (9.1%) by diet per se." (PMID 24940565, 2014). "Variables, including type of basal insulin, were collected during the first year of diagnosis of patients in a pediatric diabetes clinic." (PMID 24653838, 2014). "The regionally distinct alterations in the microbiome along the GI tract of rats with STZ-induced diabetes or insulin-treated diabetes correlated well with the regional manifestations of the diabetes-related enteric neuropathy and mesenteric capillary damage." (PMID 25469509, 2014). "In conclusion, we show that glucose intolerance (IFG, IGT, and diabetes) is frequent in early postpartum and these women have an impaired beta-cell function and lower insulin sensitivity." (PMID 25180037, 2014). "Insulin allergy is a rare and complex complication of insulin therapy in diabetic patients, with a current estimated prevalence of approximately 2.4%, depending on case reports in type 1 and type 2 diabetes mellitus patients." (PMID 25548690, 2014).
diabetes (continued). "Type 2 diabetes mellitus patients were treated with anti-diabetic drugs and/or insulin in 61.6% of cases and lipid-lowering drugs were taken by 35.2% of diabetes patients and 23.8% of NOGTT subjects." (PMID 24978196, 2014). "The extent and severity of atherosclerosis in 12-week apoE−/− mice with 6 weeks of diabetes are minimal and therefore beginning insulin at this time point corresponds to early treatment." (PMID 24829796, 2014). "A potential side effect of weight gain from insulin treatment can be troublesome, and can also promote insulin resistance, result in poorly controlled diabetes." (PMID 24620742, 2014). "The purpose of this analysis is to evaluate the safety and effectiveness of insulin initiation with once-daily insulin detemir (IDet) or insulin glargine (IGlar) in real-life clinical practice in Turkish patients with type 2 diabetes mellitus (T2DM)." (PMID 25048824, 2014). "Of the 110 patients with diabetes, 92% had type 2 diabetes, and 6% had type 1 diabetes; 24% of patients with diabetes were taking insulin." (PMID 25237398, 2014). "In the diabetes group the median HbAic level was 10.42% (interquartile range 12.1% - 7.3%), and the median number of daily insulin injections was five (interquartile range 6% - 5%)." (PMID 24460738, 2014). "The regulation of NO metabolism is particularly important in diabetes mellitus, since the activation of eNOS has been demonstrated to be under the insulin control." (PMID 24734227, 2014). "Cell-based therapy helps prevent the autoimmune destruction of β cells in T1DM, while tissue-derived stem cells such as BM-, adipose tissue-, liver- and pancreas-derived stem cells have the ability to generate insulin-producing cells, and to improve diabetes." (PMID 25364717, 2014). "Glucokinase activators (GKAs) are novel agents for diabetes which act by enhancing the formation of glucose-6-phosphate leading to increased insulin production and subsequent suppression of blood glucose." (PMID 24731772, 2014). "The present study analysed the impact of thyroid diseases on glycemic control comparing insulin-treated type 2 diabetes patients with thyroid disorder manifestation prior to, concomitant with and following diabetes onset." (PMID 24580798, 2014). "This study uses longitudinal weight data for 5,436 individuals (25,734 observations), along with markers of diabetes (fasting glucose, HbA1c, insulin and insulin resistance [HOMA-IR]) obtained in 2009." (PMID 24891020, 2014). "Diabetes mellitus is a group of metabolic disorders characterized by hyperglycaemia resulting from defects in insulin secretion, insulin action or both." (PMID 25077824, 2014). "In our mouse model, β-cells (identified by lineage tracing) showed lower insulin and increased glucagon content following 4 weeks of diabetes." (PMID 25145789, 2014). "Increasing the sensitivity of insulin signaling through anti-inflammatory therapy has become an important strategy for the development of therapeutic agents for individuals with type 2 diabetes mellitus." (PMID 25187806, 2014). "Conversely, diminished beta-cells mass and function contribute to the decrease in plasma insulin level in individuals with diabetes." (PMID 24734255, 2014). "We found that subjects with a long and chronic duration of diabetes were more likely to take insulin treatment and have reduced secretion of amylin." (PMID 25750761, 2014). "This is suggestive of great potential in the high-resolution imaging of insulin secretion, an important goal in the study of diabetes." (PMID 25580213, 2014). "The study shows that a 4-month treatment with insulin glargine or NPH insulin significantly increased the outgrowth of EPCs in patients with type 2 diabetes mellitus compared to patients who received an escalation of the oral diabetes treatment only." (PMID 25300286, 2014).
diabetes (continued). "It is thought that in individual destined to develop diabetes, at a given level of peripheral or hepatic insulin resistance, the ability of the pancreas to hypersecrete insulin is overwhelmed, and so frank diabetes ensues." (PMID 25159817, 2014). "Prevention therapy must begin much earlier than clinical diagnosis of diabetes, aiming to initially lower blood insulin levels or IR." (PMID 25069836, 2014). "Our data indicate that STZ-induced diabetes or a HFD can damage both peripheral and central nervous systems, but learning deficits develop more rapidly in insulin-deficient than in insulin-resistant conditions and only in Swiss Webster mice." (PMID 24764191, 2014). "All patients were provided with a diabetes diary at visit 1 in which daily insulin dose, daily morning fasting glucose self- measurements, one diurnal glucose profile weekly (4 pre-meal values) and possible hypoglycemic episodes were documented." (PMID 25300286, 2014). "Over-expression of tissue kallikrein-1 and modulation of the KKS shows beneficial effects on insulin sensitivity and other parameters relevant to type 2 diabetes mellitus." (PMID 25259810, 2014). "In fact, individuals with diabetes have levels of ET that would appear to be determined mainly by triglycerides and insulin." (PMID 25524258, 2014). "Galectin-3−/− mice were relatively resistant to diabetogenesis as evaluated by glycemia, quantitative histology and insulin content in streptozotocin induced diabetes." (PMID 25302080, 2014). "A recent study evaluating a support program utilizing diabetes experts and community retail pharmacists to enhance insulin prescribing in family practice came to the same conclusion." (PMID 25145469, 2014). "For example, one to two billion cardiomyocytes are required in order to treat damaged heart tissue after myocardial infarction, and about 1.3 billion insulin-producing β cells are needed to realize insulin independence for diabetes patients." (PMID 25279733, 2014). "The results showed good correlations between the scale for psychological impact of diabetes mellitus and the effectiveness of dietary therapy, exercise therapy, and pharmacotherapy with hypoglycemic agents or insulin." (PMID 25183994, 2014). "Type 2 diabetes mellitus (T2DM) is a chronic disease that comprises an array of dysfunctions resulting from the combination of resistance to insulin action and inadequate insulin secretion." (PMID 24476202, 2014). "Genome-wide association studies (GWAS) suggest a genetic basis for reductions of both insulin sensitivity and insulin secretion, phenotypes commonly observed in humans with type 2 diabetes mellitus (T2DM)." (PMID 25101872, 2014). "Impaired insulin signaling has been thought of as important step in both Alzheimer's disease (AD) and type 2 diabetes mellitus (T2DM)." (PMID 25580119, 2014). "Some GPs perceived the transition of insulin initiation to the primary care setting as an acknowledgment by health policy of their role in diabetes care." (PMID 25145469, 2014). "One PN was currently involved in diabetes education, insulin initiation and titration and others were in the process of working towards developing these skills to further develop their role in T2D management." (PMID 24479762, 2014). "This is the first study investigating the effects of add-on basal insulin treatment in a direct comparison to oral diabetes medication on endothelial progenitor cells in patients with type 2 diabetes mellitus." (PMID 25300286, 2014). "In animal models, administration of GLP-1 (3 days) increases bone formation in normal rats and rats with streptozotocin-induced diabetes or fructose-induced insulin resistance, suggesting an insulin-independent action." (PMID 25140176, 2014). "We developed KDT501, a novel substituted 1,3-cyclopentadione chemically derived from hop extracts, and evaluated it in various in vitro and in vivo models of diabetes and insulin sensitivity." (PMID 24498211, 2014).